ZNF780B (zinc finger protein 780B)
Description:
May be involved in transcriptional regulation.
Synonyms: ZNF779
Tractability: PROTAC: ubiquitination databases record sites on it.
Gene: Protein-coding gene on chromosome 19 (40,028,260 to 40,056,231, reverse strand). Ensembl gene ENSG00000128000.
Subcellular location: Nucleus
Subcellular location (Human Protein Atlas): Nucleoplasm; Centrosome
Gene Ontology:
Molecular function: DNA-binding transcription activator activity, RNA polymerase II-specific; RNA polymerase II cis-regulatory region sequence-specific DNA binding; sequence-specific double-stranded DNA binding
Biological process: regulation of transcription by RNA polymerase II; positive regulation of transcription by RNA polymerase II; regulation of DNA-templated transcription
Cellular component: nucleus
Genetic constraint (gnomAD): Loss-of-function variants: 48 observed, 70.31 expected, observed/expected ratio (o/e) 0.68, 90% interval 0.54 to 0.87. The upper end of that interval is the gene's LOEUF score, 0.87, which puts it in group 3 of 6, group 1 being the genes least tolerant of losing a copy. Missense variants: 936 observed, 1,010.4 expected, observed/expected ratio (o/e) 0.93, 90% interval 0.88 to 0.98. Synonymous variants: 311 observed, 323.78 expected, observed/expected ratio (o/e) 0.96, 90% interval 0.88 to 1.05.
Homologues: Orthologues: chimpanzee ZNF780B (90% identical). Paralogues in human: ZNF780A (67% identical), ZFP14 (34% identical), ZNF540 (34% identical), ZNF30 (34% identical), ZNF546 (33% identical), ZFP30 (33% identical), ZNF790 (33% identical), ZFP82 (33% identical), ZNF595 (33% identical), ZNF724 (32% identical), ZNF571 (32% identical), ZNF383 (32% identical), and 164 more.
Diseases named in the same sentence as ZNF780B in open-access papers:
ZNF780B is named in the same sentence as 2 diseases in open-access papers, as found by Europe PMC text mining. Sharing a sentence is not in itself a finding about the gene and the disease. The quoted sentences say what the papers report.
cancer (1 paper, 2020). A tumor composed of atypical neoplastic, often pleomorphic cells that invade other tissues. "However, there are no any reports or laboratory data on the relationship between cancer and the following genes: GSG1L, CRB1, XKR8, ZNF680, ZNF284, and ZNF780B, which is part of the 17-gene signature." (PMID 32596394, 2020). "The other six genes (GSG1 like (GSG1L), crumbs cell polarity complex component 1 (CRB1), XK-related 8 (XKR8), zinc finger protein 680 (ZNF680), zinc finger protein 284 (ZNF284), and zinc finger protein 780B (ZNF780B)) are not mentioned in the cancer research area until now." (PMID 32596394, 2020).
tumor (1 paper, 2022). "The patient-based analysis identified one additional significant gene, ZNF845 (Padj = 2.6 × 10−2), whereas the tumor-based analysis identified four, TNRC6B (Padj = 2.9 × 10−4), ZNF780B (Padj = 4.2 × 10−2), RPP30 (Padj = 6.4 × 10−2), and CASQ1 (Padj = 8.7 × 10−2)." (PMID 35922826, 2022).